MMP9 (matrix metallopeptidase 9)
Diseases named in the same sentence as MMP9 in open-access papers (continued):
Sharing a sentence is not in itself a finding about the gene and the disease.
epilepsy (continued). "We will also provide a comparison of the results of various studies on MMP-9 levels in the context of its possible use as a biomarker of the activity of epilepsy." (PMID 28104930, 2016). "Unfortunately, as for now we lack data regarding levels of MMP-9 in other groups of patients with epilepsy." (PMID 28104930, 2016). "In epilepsy, MMP-9 is suggested to play a role in epileptic focus formation and in the stimulation of seizures." (PMID 28104930, 2016). "To examine the mechanism of DNA demethylation-dependent upregulation of MMP-9 expression in epilepsy, we proceeded with the analyses of animal epileptogenesis model, known as pentylenetetrazole-induced kindling (PTZ-kindling)." (PMID 27505431, 2016). "The relation of MMP-9 with the occurrence of epilepsy was confirmed in animal models: a kainate, a pilocarpine, a 4-aminopyridine, and a pentylenetetrazole model." (PMID 28104930, 2016). "The deregulation of Mmp-9 enzymatic activity is an important molecular pathologic event facilitating the development of epilepsy." (PMID 27505431, 2016). "In the context of epilepsy the effect of MMP-9 was noted in tissue remodeling within the epileptic focus after the occurrence of seizures." (PMID 28104930, 2016). "It is likely that there are multiple targets of MMP-9 which contribute to the progression of epilepsy." (PMID 26283917, 2015). "Research has focused on the role of MMP-9 in the progression of neurologic disorders such as epilepsy, multiple sclerosis, neuroinflammatory and autoimmune disorders." (PMID 26283917, 2015). "The role of MMP-9 in epilepsy has been seen in both humans and in animals, and is a useful model of MMP-9 in aberrant plasticity." (PMID 26283917, 2015). "MMP-9 KO mice require a longer kindling period to develop epilepsy over controls, and experience less severe seizures once fully kindled and an increased survival rate." (PMID 26283917, 2015). "This indicates a functional role for MMP-9 both in synaptic pruning and in mossy fiber sprouting in rodent models of epilepsy." (PMID 26283917, 2015). "For example, diazepam, a drug used to treat epilepsy in humans, is able to suppress the development of epilepsy in kindled mice and reduce MMP-9 levels." (PMID 26283917, 2015). "Subjects with varying forms of epilepsy have an increase in the MMP-9/TIMP-1 ratio suggesting an increase in the extracellular levels of MMP-9 activity." (PMID 26283917, 2015). "In the kindling model of epilepsy, MMP9 knockout delays seizure onset while MMP9 overexpression speeds onset." (PMID 25368556, 2014). "MMP-9 has been suggested to facilitate the development of seizures by affecting epilepsy-related synaptic plasticity." (PMID 25071472, 2014). "MMP-9 was found to promote epileptogenesis in kainate-evoked and pentylenetetrazole-kindling-induced epilepsy in rats and mice." (PMID 26567100, 2014). "Slight increase in MMP-9 activity on synapses can lead to epilepsy and applying the inhibitor has potential anti-epileptic effect." (PMID 24918931, 2014). "The involvement of the MMP-9 proteolytic system has been widely studied in animal models of epilepsy." (PMID 25071472, 2014). "Increasing evidence in experimental animal models of epilepsy and human epileptic brains shows that MMP-9 plays a role in the pathogenesis of epilepsy by contributing to neuronal death, aberrant synaptic plasticity and neuroinflammation." (PMID 23829879, 2013). "Chronically elevated MMP-9 and S100B in epilepsy patients above the levels observed in age-matched controls might therefore indicate neurodegenerative processes (such as in mesial temporal sclerosis) or epileptic discharge activity." (PMID 40076533, 2025). "Epileptic seizures and being seizure-free are important trigger factors for the release of MMP-9, which may blur its status as a biomarker for epilepsy assessment." (PMID 38449733, 2024). "Four studies reported MMP-9 levels in epilepsy patients and matched controls from China." (PMID 38449733, 2024).
epilepsy (continued). "Notably, MMP-9 levels also correlated with cognitive performance in other conditions, such as attention-deficit/hyperactivity disorder, epilepsy, or systemic lupus erythematous and some studies suggested a link between elevated MMP-9 levels and dementia." (PMID 38431757, 2024). "Recent studies have shown that that the serum MMP-9 concentration in epilepsy patients was higher than that in the healthy population, which is consistent with previous reports wherein the serum levels of MMP-9 in epilepsy patients were significantly higher after seizures." (PMID 38449733, 2024). "Eight studies reported serum MMP-9 levels in epilepsy patients and matched controls." (PMID 38449733, 2024). "Moreover, the subgroup analysis of age category indicated that the serum MMP-9 level of adult patients with epilepsy was significantly higher than that of matched controls." (PMID 38449733, 2024). "When activated by an injury in the context of epilepsy, MMP-9 initiates several processes, including the disruption of the blood–brain barrier, the promotion of neuroinflammation, modulation of synaptic plasticity, and the augmentation of neuronal excitability." (PMID 38255970, 2024). "Moreover, the serum levels of the metalloproteinases (MMP3 and MMP9) were elevated in the epilepsy group compared to the control group with significant differences." (PMID 39268188, 2024). "This study aims to evaluate and quantify the correlation between MMP-9 levels and epilepsy." (PMID 38449733, 2024). "The serum level of MMP-9 is elevated in patients with epilepsy, particularly in adults." (PMID 38449733, 2024). "A set of molecules associated with BBB permeability (MMP-2, MMP-9, S100B), restoration (TIMP-1, TIMP-2, TSP-2), neuroinflammation (CCL-2), and endothelial activation (ICAM-1, P-sel) that are affected in epilepsy and can be measured in blood was selected in this study." (PMID 36766708, 2023). "The molecules whose levels are chronically elevated in serum of patients with epilepsy (MMP-2, MMP-9, S100B, TIMP-1, TIMP-2) might be considered diagnostic biomarkers of epilepsy." (PMID 36766708, 2023). "Finally, MMP9 and C3aR1 were identified as hub genes, and RT-PCR confirmed that the expression levels of the hub genes were higher in epilepsy and SAH samples than in normal samples." (PMID 36741285, 2023). "With those limitations, serum MMP-9 in patients with epilepsy might be considered a biomarker of seizure prediction." (PMID 36499038, 2022). "The role of MMP-9 in neuronalplasticity has already been well-studied, and its influence on this process hasbeen documented in memory and learning and various pathological neuropsychiatricconditions, such as schizophrenia, addiction, or epilepsy." (PMID 35061219, 2022). "In particular, dysregulation of MMP-9 is known to influence cognitive processes and increased MMP-9 levels are associated with several neurodevelopmental disorders including ASD, fragile X syndrome, epilepsy, bipolar disorder, and schizophrenia." (PMID 34282726, 2021). "In the PTZ kindling mouse model of epilepsy, enhanced hippocampal expression of MMP-9 was found to be associated with increased levels of mBDNF, while downregulation of this neurotrophic factor was observed in kindled MMP-9-deficient mice." (PMID 33467671, 2021). "While in MMP-9-overexpressing mice epilepsy development was augmented." (PMID 33277582, 2020). "MMP-9 is upregulated in several epilepsy animal models as well as in epileptic patients." (PMID 32372941, 2020). "In addition, in humans with different types of epilepsy, the occurrence of the seizures is correlated with the elevated levels of MMP-9 in serum or plasma as well as in the cerebrospinal fluid." (PMID 31172215, 2019).
epilepsy (continued). "MMP-9 knockout mice were less sensitive to pentylenetetrazol (PTZ) kindling-induced epilepsy, with a simultaneous decrease of mossy fiber synaptogenesis, while MMP-9 overexpression results in increased dendritic spine proliferation and the misposition of synaptogenesis in the hippocampus." (PMID 31312171, 2019). "Studies on animals were supplemented with clinical data demonstrating that in human patients with different types of epilepsy, occurrence of chronic seizures is correlated with the elevated levels of MMP-9 in serum, plasma, and cerebrospinal fluid as well as in the brain." (PMID 30298130, 2018). "While we do not emphasize inflammatory response pathways in the present review, these may be crucial in understanding MMP-9 dysregulation in CNS disorders as there is evidence for neuro-inflammation in injury models, AD, epilepsy, and schizophrenia." (PMID 30123106, 2018). "Since high levels of MMP-9 are associated with neuronal death, aberrant synaptic plasticity, and inflammation during epileptogenesis, MMP-9 has become a potential therapeutic target in epilepsy." (PMID 30044455, 2018). "Understanding the neurobiology of cytokines, chemokines, MMP-9, and adhesion molecules, overlapping with neuronal network physiology, will allow for greater development of treatment and prophylactic measures against epilepsy." (PMID 29764485, 2018). "Therefore, we demonstrated a significant functional role for MMP-9 in post-TBI processes that lead to the development of epilepsy." (PMID 29667129, 2018). "MMP-9 may contribute to epilepsy through mechanisms that involve synaptic plasticity, neuroinflammation, and blood-brain barrier disruption." (PMID 29667129, 2018). "It seems that the activity of MMP-9 in epilepsy is multidirectional." (PMID 28104930, 2016). "Moreover the mean MMP-9 to TIMP-1 ratio was higher in patients with worse control of epilepsy (defined by authors as a minimum of 28 seizures during four weeks) than in the patients in whom lower number of seizures was observed." (PMID 28104930, 2016). "It is being suggested that, in some models of epilepsy, MMP-9 contributes to cell death." (PMID 28104930, 2016). "Mechanisms controlling the upregulation of Mmp-9 expression during epileptogenesis and in epilepsy are unknown." (PMID 27505431, 2016). "Interestingly, an increase of MMP-9 activity was also reported in the unchanged tissue of patients with epilepsy." (PMID 28104930, 2016). "In epilepsy, both experimental research and clinical studies indicate that MMP-9 contributes to formation of epileptic focus, activation of inflammation processes after the occurrence of epileptic seizures via modification of blood-brain barrier and cell death." (PMID 28104930, 2016). "According to recent studies, MMP-9 seems to be a key factor in pathogenesis of epilepsy." (PMID 28104930, 2016). "Yet the knowledge about MMP-9 and its role in epilepsy needs further deepening." (PMID 28104930, 2016). "In the next experiment, we have asked whether epigenetic molecular mechanisms other than DNA methylation and DNA hydroxymethylation could be involved in a regulation of Mmp-9 expression during epilepsy development in the hippocampus." (PMID 27505431, 2016). "Consequently, blockage of epilepsy development should lead to an inhibition of epileptogenesis-dependent demethylation of Mmp-9 promoter, and consequently to prevention of Mmp-9 mRNA upregulation." (PMID 27505431, 2016). "Moreover, dizocilpine-dependent inhibition of epileptogenesis also fully prevented PTZ kindling–evoked demethylation of Mmp-9 proximal promoter, suggesting that this demethylation is strictly related to epilepsy development." (PMID 27505431, 2016). "Regulation of Mmp-9 expression and development of epilepsy are both NMDA receptor–dependent." (PMID 27505431, 2016).
epilepsy (continued). "To evaluate the possibility that this phenomenon is involved in the control of MMP-9 mRNA upregulation in human epilepsy, we investigated by methylated DNA immunoprecipitation (MeDIP) whether the proximal MMP-9 promoter was demethylated in epileptic patients." (PMID 27505431, 2016). "The authors noted that MMP-9 may exacerbate pathological processes occurring after seizures and lead to drug-resistant epilepsy." (PMID 28104930, 2016). "One mechanism thought to underlie epilepsy progression may be through a change in the ratio of MMP-9 to TIMP-1, the endogenous inhibitor of MMP-9." (PMID 26283917, 2015). "In young and adult human epilepsy patients MMP-9 protein levels are higher compared to controls." (PMID 26283917, 2015). "MMP-9 activity was also considerably enhanced in other epilepsy models that do not involve neuronal cell loss." (PMID 25071472, 2014). "Considering the extant evidence, MMP-9 might play a dual role in epilepsy, with distinct roles in pathogenesis at various time-points after seizures." (PMID 25071472, 2014). "The increase in MMP-9 produced by albumin further implicates both astrocytes and albumin in the acute and long-term complications of acute CNS insults, including cerebral edema and epilepsy." (PMID 22507553, 2012). "MMP-9 KO mice show increased resistance to pentylenetetrazole kindling–induced epilepsy." (PMID 22507553, 2012). "Neuronal MMP-9 participates in synaptic plasticity by controlling the shape of dendritic spines and the function of excitatory synapses, and if not released properly, MMP-9 can cause a variety of brain diseases, including epilepsy, schizophrenia, and neurodegeneration." (PMID 40423426, 2025). "The serum level of MMP-9 could potentially serve as a biomarker for epilepsy." (PMID 38449733, 2024). "Multiple studies have explored the associations between miRNA-212 and epilepsy, but very few studies have explored the association between the lncRNA ILF3AS1 and epilepsy, considering that miRNA-212 is targeted by lncRNA ILF3AS1, causing boomback effects on MMP3 and MMP9." (PMID 39268188, 2024). "Additionally, the subjects had different types of seizures and were taking different types of epilepsy drugs, which could have varying effects on serum MMP-9 levels." (PMID 38449733, 2024). "We showed that serum levels of molecules associated with BBB disruption (MMP-2, MMP-9, S100B) and restoration (TIMP-1, TIMP-2) are increased in patients with epilepsy in the interictal period, which might reflect chronic processes taking place at the BBB, even in the absence of seizures." (PMID 36766708, 2023). "The observed influence of serum MMP-9 on seizure count might suggest that this molecule contributes to seizure generation in patients with epilepsy, yet it is still unclear which of its mechanisms of action prevail and if the serum level of MMP-9 reflects MMP-9 activity in the CNS." (PMID 36499038, 2022). "MMP-9 has been repeatedly shown to play a pivotal role in both physiological and aberrant synaptic plasticity and shown to contribute to epileptogenesis, in which it is rapidly and transiently activated by pro-epileptogenic insults and functionally involved in epilepsy development." (PMID 33277582, 2020). "Using this hypothesis as a scaffold, we bring together evidence from studies of schizophrenia, AD, and epilepsy to suggest that systematic studies of the interplay between MMP-9, PNN and PV cells may be key to understanding mechanisms of multiple CNS disorders at the cellular and circuit levels." (PMID 30123106, 2018). "In addition, MMP-9 cleavage of pro-BDNF into mature BDNF may play a role in the development of epilepsy through mossy fiber sprouting." (PMID 26283917, 2015). "However, the first indication that MMP-9 may play a role beyond the pathology of the brain came from research on the kainate-induced epilepsy models in mice." (PMID 25071472, 2014).
epilepsy (continued). "A previous study involving 145 poststroke epilepsy patients compared a LTG plus VPA treatment group and a VPA-only group in terms of the serum HMGB-1, matrix metalloproteinase (MMP)-9, and IL-6 levels." (PMID 40806813, 2025). "Neurological manifestations of the disease, such as epilepsy and neuropsychiatric disorders, can be related to the inhibition by ECM1 of MMP-9 activity, a 10a protein that is strongly expressed in the brain." (PMID 39697925, 2024). "Previous studies using the rat pilocarpine model of TLE have reported downregulation of tight junction proteins and upregulation of matrix metalloproteinases Mmp2 and Mmp9 in brain capillary tissue after 48 h, leading to BBB dysfunction in epilepsy." (PMID 39040630, 2024). "Serum levels of MMP-9, MMP-2, TIMP-1, TIMP-2 and S100B were higher in patients with epilepsy in comparison to control group (p < 0.0001; <0.0001; 0.001; <0.0001; <0.0001, respectively)." (PMID 36766708, 2023). "The roles of MMP-9 and C3AR1 in the pathogenesis of epilepsy have been reported previously, but the mechanisms of the genes associated with SAH-induced epilepsy had not been studied." (PMID 36741285, 2023). "Serum levels of MMP-9, MMP-2, TIMP-1, TIMP-2 and S100B are elevated in patients with epilepsy in the interictal period, which suggests chronic processes of BBB disruption and restoration." (PMID 36766708, 2023). "The results showed that the expression of MMP9 and C3AR1 was higher in SAH patients than in normal individuals and that the incidence of epilepsy in SAH patients with significant expression of these two IRGs was significantly higher." (PMID 36741285, 2023). "Serum levels of MMP-9, MMP-2, TIMP-1, TIMP-2, S100B, CCL-2, ICAM-1, P-selectin, and TSP-2 were examined in a group of 49 patients with epilepsy who were seizure-free for a minimum of seven days and measured by ELISA." (PMID 36499038, 2022). "In KA-evoked epilepsy and PTZ kindling-induced epilepsy rodent studies, it is shown that both the MMP9 protein expression and enzymatic activity become strongly increased upon seizures." (PMID 36289737, 2022). "It is known that PTZ-induction increases the expression of MMP-9 and that the selective inhibition of MMP-9 confers neuroprotection in patients with epilepsy." (PMID 33498927, 2021). "Synaptic transmission is also influenced via MMP-9 by NMDA and AMPA glutamate receptors, reducing its efficacy after multiple seizures, as observed in 4-aminopyridine (4-AP) induced epilepsy model." (PMID 31312171, 2019). "In one of the newer studies levels of matrix metalloproteinases (among them MMP-9), oxidative stress and LDH were checked in saliva of children with epilepsy." (PMID 28104930, 2016). "The increase of MMP-9 and ICAM-1 was similar in all patients with epilepsy and correlated with the intensity of seizures." (PMID 28104930, 2016). "In addition, we also checked by ChIP whether H3K9me2 and H3K9me3, the other histone modifications that are abundant in neurons and their progenitors exert transcriptionally repressive action, can be involved in a regulation of MMP-9 expression during the development of epilepsy in vivo." (PMID 27505431, 2016). "None of the genome-wide studies found differential methylation of MMP-9 promoter or DNA methylation dependent regulation of MMP-9 expression both during epileptogenesis and in epilepsy in rodents and humans." (PMID 27505431, 2016). "Two studies reported that the serum MMP-9 level in children with epilepsy was not significantly different from that in the control group (p = 0.09)." (PMID 38449733, 2024). "The patient duration of seizure subgroup analysis showed that the serum MMP-9 levels at 1–3, 24, and 72 h after seizure in female and male epilepsy patients showed no substantial difference between with the control group." (PMID 38449733, 2024). "MMP3 and MMP9 expressions are known to be promoted by ILF3AS1 overexpression, leading to the hypothesis that MMP inhibitors could be reliable treatments for epilepsy." (PMID 39268188, 2024).